NRROS (negative regulator of reactive oxygen species)
Description:
Key regulator of transforming growth factor beta-1 (TGFB1) specifically required for microglia function in the nervous system (By similarity). Required for activation of latent TGF-beta-1 in macrophages and microglia: associates specifically via disulfide bonds with the Latency-associated peptide (LAP), which is the regulatory chain of TGFB1, and regulates integrin-dependent activation of TGF-beta-1 (By similarity). TGF-beta-1 activation mediated by LRRC33/NRROS is highly localized: there is little spreading of TGF-beta-1 activated from one microglial cell to neighboring microglia, suggesting the existence of localized and selective activation of TGF-beta-1 by LRRC33/NRROS (By similarity). Indirectly plays a role in Toll-like receptor (TLR) signaling: ability to inhibit TLR-mediated NF-kappa-B activation and cytokine production is probably a consequence of its role in TGF-beta-1 signaling.
Synonyms: LRRC33; UNQ3030; ELLP3030; MGC50789; GARPL1; SENEBAC
Tractability: Antibody: UniProt places it where antibodies can reach, with high confidence; UniProt predicts a signal peptide or a membrane-spanning region; its Gene Ontology location is reachable by antibodies, with medium confidence. PROTAC: ubiquitination databases record sites on it.
Gene: Protein-coding gene on chromosome 3 (196,639,694 to 196,662,004, forward strand). Ensembl gene ENSG00000174004.
Subcellular location: Cell membrane; Endoplasmic reticulum membrane
Gene Ontology:
Molecular function: transforming growth factor beta binding; receptor ligand inhibitor activity
Biological process: immune response; inflammatory response; innate immune response; microglia development; positive regulation of transforming growth factor beta receptor signaling pathway; superoxide metabolic process; transforming growth factor beta receptor signaling pathway
Cellular component: cell surface; endoplasmic reticulum membrane; plasma membrane; endoplasmic reticulum
Genetic constraint (gnomAD): Loss-of-function variants: 7 observed, 14.47 expected, observed/expected ratio (o/e) 0.48, 90% interval 0.27 to 0.91. The upper end of that interval is the gene's LOEUF score, 0.91, which puts it in group 3 of 6, group 1 being the genes least tolerant of losing a copy. Missense variants: 853 observed, 930.12 expected, observed/expected ratio (o/e) 0.92, 90% interval 0.87 to 0.97. Synonymous variants: 458 observed, 432.11 expected, observed/expected ratio (o/e) 1.06, 90% interval 0.98 to 1.14.
Gene-disease validity (ClinGen):
ClinGen rates the evidence that NRROS causes each of these diseases.
seizures, early-onset, with neurodegeneration and brain calcifications (autosomal recessive): Definitive.
Homologues: Orthologues: chimpanzee NRROS (98% identical), macaque NRROS (95% identical), pig NRROS (82% identical), mouse Nrros (81% identical), rabbit NRROS (80% identical), rat Nrros (80% identical), guinea pig NRROS (71% identical), dog NRROS (67% identical), tropical clawed frog nrros (43% identical), zebrafish nrros (36% identical). Paralogues in human: LRRC32 (33% identical), TLR7 (22% identical), TLR8 (22% identical), CD180 (22% identical), TLR3 (21% identical), IGFALS (21% identical), TLR5 (19% identical), TLR2 (17% identical), TLR6 (16% identical), TLR4 (16% identical), VASN (16% identical), TLR1 (16% identical), and 10 more.
Diseases named in the same sentence as NRROS in open-access papers:
NRROS is named in the same sentence as 17 diseases in open-access papers, as found by Europe PMC text mining. Sharing a sentence is not in itself a finding about the gene and the disease. The quoted sentences say what the papers report.
Autoimmunity (1 paper, 2019). The occurrence of an immune reaction against the organism's own cells or tissues. "In previous researches, LRRC33 is known as the Negative Regulator of Reactive Oxygen Species (NRROS), and its function is down-regulating of reactive oxygen species during host defense and autoimmunity on gene knock-out mice." (PMID 31600200, 2019).
brain inflammatory disease (1 paper, 2022). An inflammatory disease involving a pathogenic inflammatory response in the brain. "Our data indicated that constitutive expression of human NRROS reduced the H2O2-induced Nox/ROS generation, which protected against brain inflammatory diseases." (PMID 34997457, 2022).
cervical cancer (1 paper, 2021). A primary or metastatic malignant neoplasm involving the cervix. "Some hotspot genes (e.g., KLF5, LRP1B, and KLF12) have previously been described in cervical cancer, and others (e.g., CADM2, CEP19, CSMD1, and NRROS) are reported for the first time in the present study." (PMID 34885212, 2021).
fungal infections (1 paper, 2022). "This QTL region harbors the NRROS gene, which is related to host defense against bacterial and fungal infections." (PMID 35100362, 2022).
Leukodystrophies (1 paper, 2021). "Leukodystrophies related to bi-allelic loss-of-function mutations in CSF1R, TREM2, TYROBP, LRRC33/NRROS or USP18 can be categorized as primary microgliopathies." (PMID 34282843, 2021).
vitiligo (1 paper, 2023). Generalized well circumscribed patches of leukoderma that are generally distributed over symmetric body locations and is due to autoimmune destruction of melanocytes. "Previous studies on Caucasian and Chinese Han cohorts also reported a significant association between the T allele of rs6583331 SNP of NRROS and vitiligo." (PMID 37239478, 2023). "However, in our cohort, a novel vitiligo-associated variant of NRROS was identified." (PMID 37239478, 2023).
infection (2 papers, 2021 to 2025). The state of being infected such as from the introduction of a foreign agent such as serum, vaccine, antigenic substance or organism. "The NRROS protein regulates ROS production by phagocytes during inflammatory response, allowing phagocytes to produce high amounts of ROS in case of infection, while minimizing host's tissue damage." (PMID 33777020, 2021).
neurodegenerative disease (1 paper, 2022). A disorder of the central nervous system characterized by gradual and progressive loss of neural tissue and neurologic function. "Based on these findings, we found the first time that up-regulation of NRROS by 15d-PGJ2 provides useful therapeutic strategies for brain injury, inflammation, and neurodegenerative diseases." (PMID 34997457, 2022).
NRROS also shares sentences with these, for which no sentence is quoted: cancer (3 papers); tumor (3); acute myeloid leukemia (1); asthma (1); autoimmune disease (1); E. coli infection (1); experimental autoimmune encephalomyelitis (1); myeloid leukemia (1); neurological disorders (1).